RNU6-279P (RNA, U6 small nuclear 279, pseudogene)
Gene: Small nuclear RNA gene on chromosome 12 (59,369,051 to 59,369,151, reverse strand). Ensembl gene ENSG00000212599.
Homologues: Orthologues: chimpanzee U6 (91% identical), macaque U6 (82% identical), guinea pig U6 (78% identical), rat LOC120094561 (74% identical), rabbit U6 (52% identical). Paralogues in human: RNU6-338P (81% identical), RNU6-1011P (80% identical), RNU6-1060P (80% identical), RNU6-116P (80% identical), RNU6-12P (80% identical), RNU6-13P (80% identical), RNU6-32P (80% identical), RNU6-33P (80% identical), RNU6-47P (80% identical), RNU6-698P (80% identical), RNU6-7 (80% identical), RNU6-8 (80% identical), and 1286 more.